APOA1 (apolipoprotein A1)
Diseases named in the same sentence as APOA1 in open-access papers (continued):
Sharing a sentence is not in itself a finding about the gene and the disease.
infection (75 papers, 2007 to 2026). The state of being infected such as from the introduction of a foreign agent such as serum, vaccine, antigenic substance or organism. "A decrease in serum ApoA-1 concentrations was associated with higher illness severity, lethality, and susceptibility to infection in critical patients in human medicine." (PMID 41437958, 2025). "Higher levels of both HDL and apoA1 were associated with a lower incidence of infection as well as a lower incidence of severe disease." (PMID 37372137, 2023). "High values of apoA1 were also negatively associated with infection (OR = 0.99, p < 0.001)." (PMID 37372137, 2023). "ApoA1 contributes to innate immune responses by enhancing pathogen clearance and potentially serves as a biomarker for infections." (PMID 40853910, 2025). "The serum ApoA1 level at the initial diagnosis was significantly correlated with the severity and prognosis of omicron infections." (PMID 40809523, 2025). "Pregnancy reduced the infection risk (OR = 0.82, p < 0.001) only in the HDL group, while smoking reduced the risk in both groups (OR = 0.39 for the HDL group, and OR = 0.32 for the apoA1 group; both p < 0.001)." (PMID 37372137, 2023). "Smoking was consistently negatively associated with infection (10% vs. 4% for the HDL group and 22% vs. 8% for the apoA1 group; both p < 0.001)." (PMID 37372137, 2023). "Females had a higher risk of infection (OR = 1.21 for the HDL group and OR = 1.39 for the apoA1 group; both p < 0.001)." (PMID 37372137, 2023). "More specifically, our results indicated that an increase in the values of HDL and apoA1 reduces the odds of the infection by 2% and 1%, respectively, after adjusting for demographic covariates and comorbidities." (PMID 37372137, 2023). "The expression of apoa-1 and apoa-14 were upregulated in the foregut, midgut, and hindgut of common carp post the second infection." (PMID 36466906, 2022). "APOA1 is considered a good predictor of infectious disease in pigs, due to levels dropping rapidly when the infection appears." (PMID 36430174, 2022). "We identified that both ABCA1 and APOA1 genes are induced in the first 2–6 h of Mo-DC infection, and still occurs following infection with the ΔactAΔgcpE strain." (PMID 34381163, 2021). "Our observations raise important questions with respect to the underlying biological mechanisms through which HDL-cholesterol and ApoA1 protect against infection by SARS-CoV-2 (and other pathogens)." (PMID 33667465, 2021). "In this study we found higher serum levels of anti-apoA-1 IgG in patients with HCV genotype 3 infection, which needs confirmation in a larger cohort." (PMID 29423541, 2018). "In a similar model in mice, ApoA1 dosed 1 h post-infection via intravenous (IV) infusion at 100 mg/kg increased both 3-day survival rate and overall survival time versus saline-treated controls." (PMID 26557091, 2015). "When administered at 10 mg/kg (IP) 1 h post-infection, ApoA1 increased the 5-day survival rate from 0 to 90% in rats given 5 mg/kg LPS." (PMID 26557091, 2015). "We further analyzed the relationship between SA, ApoA1 levels and past infection determined by histological examination of placenta tissue." (PMID 20098675, 2010). "Carpintero and co-workers found a decreased levels of ApoA1 in pig sera after 2–4 days of infection with A. pleuropneumoniae or Streptococcus suis." (PMID 17466061, 2007). "Transporters such as ABCA1 and APOA1 have been proposed to export IPP and ABCA1, but not APOA1 expression, is reduced in human dendritic cells when mevastatin is used during an infection with HMBPP-deficient L. monocytogenes mutants." (PMID 40667022, 2025). "However, the pathophysiology of decrease in ApoA-1 concentrations accompanied by an infection/inflammation is still unclear and most likely multifactorial." (PMID 41437958, 2025).
infection (continued). "Asians had a lower risk of infection than Whites in both groups (OR = 0.45 in the HDL group, and OR = 0.24 for the apoA1 group; both p < 0.001) while African Americans (OR = 1.03, p < 0.001) and Hispanics (OR = 1.19, p < 0.001) had a greater risk of infection in the HDL group." (PMID 37372137, 2023). "In contrast to the infection case, being female reduced the risk of having a severe disease in both groups (58% vs. 53% with p < 0.001 for the HDL group and 55% vs. 47% with p = 0.06 for the apoA1 group, which is significant only at the 10% level)." (PMID 37372137, 2023). "From bioinformatic analysis, we identified three significant genes (GCG, APOA1, and IGFBP1) associated with the infection of H. pylori, and the survival nomogram based on the H. pylori-related genes exhibited good predictive power for survival outcome among GC subjects." (PMID 37846989, 2023). "For the NMR metabolomic measures considered in mediation models, there was evidence of an indirect effect of infection mediated by GlycA on all measures, and an indirect effect mediated by hsCRP for phenylalanine, ApoA1, and the HDL, HDL2, and HDL3 cholesterols." (PMID 35535496, 2022). "Interestingly, apoa-1 and apoa-14 were first downregulated and then upregulated during the infection process, which was consistent with the findings of a previous study in carp infected with SVCV." (PMID 36466906, 2022). "A previous study demonstrated that after infection with Salmonella (a Gram-negative bacterium that expresses LPS), the plasma levels of IFNβ significantly increase in ApoA1 deficient mice compared with wild-type mice." (PMID 33589571, 2021). "To determine whether Lm induction of the ABCA1 gene and APOA1 was dependent on phosphoantigen production in the cells we blocked production with mevastatin in conjunction with infection and determined gene induction." (PMID 34381163, 2021). "For example, HDL-cholesterol can protect against infections by a variety of pathogens, including bacteria and parasites, and can directly bind and neutralize various DNA and RNA viruses through ApoA1-mediated inhibition of viral fusion and entry into host cells." (PMID 33667465, 2021). "Continuously low levels of HDL-C and apoA1 hint at an uncontrolled infection." (PMID 27462492, 2016). "Additionally, it was found that ApoA1 overexpressing mice were more resistant to infection than those with normal or decreased levels of circulating ApoA1." (PMID 26557091, 2015). "Notably, IL-6 inflammatory factor, CASP8, and APOA1 may also be the key genes with altered expression after pathogen infection, which are closely related to the inflammatory response to tracheal injury in calves." (PMID 40005807, 2025). "In addition, SARS-CoV-2pp infection decreased the secretion of apoB and apoA1 in transduced cells." (PMID 38727305, 2024). "On the other hand, five genes were down-regulated, that are involved in lipid transport and metabolism (ApoA1, ApoB), apoptosis (Birc3), and blood clotting (coagulation) (Fga, Fgb), potentially indicating an attempt to control lipid accumulation and plaque growth induced by infection." (PMID 26619277, 2015). "In particular, we identified a unique cholesterol efflux signature, marked by the secretion of APOA1 and PON1, in response to Mycobacterium Tuberculosis, consistent with the metabolic reprogramming that takes place during infection." (PMID 42214753, 2026). "Specifically, the addition of FUC caused a further reduction in mRNA expression levels of NHE2, TRPV6, APOA1, APOA4, APOB, APOC3, and ASS1 compared to PEDV infection alone, while FUC supplementation counteracts PEDV-induced ARG1 upregulation." (PMID 40218394, 2025). "Following infection with ADV-ApoA1, 4T1 and MDA-MB-231 cells efficiently expressed and secreted ApoA1 protein." (PMID 38566092, 2024). "In patients with cirrhosis, ApoA1 and HDL3 levels were significantly lower in patients who developed severe infection." (PMID 35327501, 2022).
infection (continued). "Analogous relationships were observed between infection and 6-month inflammation, HDL cholesterol, and apolipoprotein A1." (PMID 35535496, 2022). "Estimated effect sizes were generally similar across most sensitivity analyses, though excluding samples with processing time greater than 4 hr slightly reduced the magnitude of estimated effects of parent-reported infections on HDL cholesterols and ApoA1." (PMID 35535496, 2022). "For all measures except ApoA1 and HDL3 cholesterol, GlycA was estimated to mediate a larger proportion of the total effect of infections on metabolomic measures than hsCRP." (PMID 35535496, 2022). "We found that during the first hours of infection of Mo-DC there is a change in the transcription of genes involved in cholesterol biosynthesis and export (ABCA1 and ApoA1) that would result in an increase in the intracellular IPP pool." (PMID 34381163, 2021). "During infection and inflammatory response, SAA proteins increase and replace ApoA-1 in HDL particles." (PMID 34205975, 2021). "This was confirmed at the protein level, as infection decreased the amount of secreted AHSG and apolipoproteins APOA1, APOE and APOH, in both HepG2 and Huh7 conditioned media, as well as of APOB, APOC3 and SERPINF2 in Huh7." (PMID 34858876, 2021). "Ten (71%) of the 14 patients were consistently positive for ApoA-1 IgG, five (83%) out of the six patients with HCV genotype 1 infection and five (63%) out of the eight patients with HCV genotype 3 infection." (PMID 29423541, 2018). "Infection also down-regulated genes of the FXR pathway (e.g., NR1H4, FABP6, APOA1, SLC10A2), indicating disruption of the bile acid absorption in ileum." (PMID 26738723, 2016). "As seen in infection with HCVcc (JFH1), expression of ApoA1, ApoA2, ApoC1, ApoC2, ApoC3 and ApoE enhanced the formation of infectious particles of TH/JFH1 and S310/JFH1 chimeric viruses." (PMID 25502789, 2014). "Group C had low IL-6 expression and high APOA1 expression when not infected with the pathogen, and the two were inversely adjusted after infection in line with the results of the previous investigations." (PMID 40005807, 2025). "Pregnancy was negatively associated with infection for the HDL group (4.2% vs. 3.9%, p < 0.001), while it was not significant for the apoA1 group (p = 0.31)." (PMID 37372137, 2023). "ApoA-1 was up-regulated from 10 dpi onwards using ARP0 as reference gene whereas, using EF1α no significant change was observed in any of the time point post infection." (PMID 36792637, 2023). "Indeed, ApoA1 and HDL3 have strong translational potential in the understanding of T2DM, NASH, and severe infection." (PMID 35327501, 2022). "All other markers (CCL4, IL-1Ra, TNF, S100A12, ferritin, C1q, CRP, and ApoA1) yielded no or hardly any detectable signals or failed to discriminate before and after infection (ApoA1, C1q)." (PMID 34943175, 2021). "Increased expression of APOA1 and APOA4 may also represent a more general response to infection." (PMID 31555604, 2019). "In chickens ApoA1 responds as a negative acute phase protein (O’Reilly, E. L., unpublished observation) as it does in other species reducing its concentration in plasma as a result of inflammation and infection." (PMID 28572745, 2016). "Although we have not shown significant quantitative changes in ApoA1, the PC composition of HDL may be altered by HCV-G1 infection." (PMID 35365728, 2022). "Importantly, we did not detect induction of the APOA1 gene and only a modest induction of the ABCA1 gene following infection with the Δhly strain, suggesting that cytosol invasion was essential to augment the expression of these two genes." (PMID 34381163, 2021).
metabolic disorders (24 papers, 2008 to 2026). "The cases of LCAT and apoA1 deficiencies demonstrate the diverse phenotypic spectrum of HDL-C-related metabolic disorders, highlighting how early genetic screening can guide clinical management and follow-up strategies." (PMID 40476138, 2025). "Several studies have also suggested that an elevated ApoB/ApoA1 ratio is a more powerful predictor than other lipid fractions for metabolic disorders, including T2DM." (PMID 32505210, 2020). "Presently, the available data are insufficient to assess whether the supplementation of HF diets with n-3 PUFA, carried either by PO or FO, can make any difference in the apoA-1 metabolic outcomes, with the aim of preventing or treating metabolic disorders." (PMID 27101976, 2016). "First, we found that odd-chain SFAs were favourably associated with markers of lipids (with exceptions for HDL-C and ApoA1), liver function and chronic inflammation, which we postulated might contribute to the inverse association of odd-chain SFA with cardio-metabolic diseases." (PMID 29145892, 2017). "In addition, we found that many genes are related to metabolic diseases, such as AKT was involved in glucose metabolism, APOA1 was related to lipid metabolism, and HP1BP3 seem to be associated with thyroid disease." (PMID 33067549, 2020). "In that ApoA1, the largest component of HDL, and ApoB, which reflects the amount of triglyceride-rich LDL, are meaningful factors in relation to metabolism, the levels of these molecules may explain the state of metabolic diseases like MASLD." (PMID 40507912, 2025). "Maternal metabolic disease did not affect expression of lipid transporter proteins, including ApoA1, ApoB and SR-B1, consistent with our earlier report that expression of glucose and fatty acid transporter genes was also unchanged in diabetic pregnancy-derived yolk sacs." (PMID 36936697, 2023).
kidney disease (17 papers, 2014 to 2025). "The mediation analysis was performed testing several variables known to be linked to kidney disease, including C-reactive protein, IL-6, uric acid, azotemia, triglycerides, ApoA1, ApoB, and HbA1c, and that resulted associated with mitokines, (data not shown)." (PMID 33131010, 2021). "The top 18 indicators ranked by their importance in the model were as follows: MAP, chronic hypertension, UIBC, kidney disease, proteinuria, BMI, TIBC, HDL-C, ApoA1, ALB, Fn, C4, CHO, GLO, Cr, Fe, TG and Ca." (PMID 40002760, 2025).
heart disease (13 papers, 2008 to 2025). "The exposure of 57 workers to As showed that there is an increased level of the lipoprotein (a) (LP(a)), a ratio of apolipoprotein-B (Apo-B)/apolipoprotein-A1 (Apo-A1) and Apo-B level and a decreased level of Apo-A1, indicative of high-risk of heart diseases." (PMID 36080424, 2022). "While elevated levels of apoB and reduced levels of apoA1 are associated with increased cardiac disease, serum levels of apoB100 associated VLDL are regulated in turn by Acat2 which stimulates cholesteryl ester secretion into apoB-containing lipoproteins." (PMID 18959802, 2008). "A retrospective observational study used machine learning models to cluster participants based on lipid profile abnormalities such as elevated lipoprotein (a), decreased high-density lipoprotein cholesterol (HDL-C), and apolipoprotein A1, which are common causes of heart disease." (PMID 40911117, 2025). "It is predicted that APOA1 gene rs670 and rs5069 polymorphisms may cause heart disease by raising systolic blood pressure and plasma glucose levels." (PMID 39295604, 2024). "There is some evidence that APOA1 rs1799837 polymorphism may be associated with heart disease by causing a decrease in HDL levels." (PMID 39295604, 2024). "The 11q23-24 human genome location is well known for a cluster of genes (APOA1, APOC3, APOA4, and APOA5), which effect the lipid levels as well as is associated with DM and heart disease." (PMID 19038053, 2008). "The APOA1 rs5069 allele was associated with high HDL cholesterol and low triglyceride levels, while the APOA1 rs1799837 allele was associated with HDL cholesterol level and heart disease." (PMID 39295604, 2024).
inflammation (13 papers, 2007 to 2025). Aberrant reaction of the microcirculation characterized by movement of fluid and leukocytes from the blood into extravascular tissues. "APOA1 can also regulate host immune responses and promotes tight junction formation to resolve allergen-induced airway inflammation, which could indicate multiple roles for these proteins in modulating the host-pathogen interaction in the intestinal epithelium." (PMID 31555604, 2019).
neurological disorders (13 papers, 2011 to 2025). "Altered cholesterol, HDL and LDL metabolism, gene variants of APOA1, APOB, and APOE4, and decreased ApoA1 levels have been implicated in other neurologic disorders." (PMID 34504056, 2021). "In the fetal human brain, tau protein does not have N-terminal insertions, and 2N-Tau interacting proteins, such as apoA1, were specifically associated with neurological disease." (PMID 34575888, 2021). "It is noteworthy that indicators reflecting liver function, such as DBIL, NBIL, TP, and ALB, along with markers associated with liver glucose and lipid metabolism, such as GLU and APOA1, play significant roles in predicting nervous system diseases." (PMID 40739302, 2025). "We found that the numerical distribution of GLU, CK, APOA1, and K could serve as important features for distinguishing different nervous system diseases." (PMID 40739302, 2025). "At the same time, a network displaying the intersection features among various nervous system diseases showed that GLU, creatine kinase (CK), APOA1, and K were the top 4 features subdividing various nervous system diseases." (PMID 40739302, 2025).
neurodegenerative disease (10 papers, 2011 to 2025). A disorder of the central nervous system characterized by gradual and progressive loss of neural tissue and neurologic function. "In our study, we present five proteins that are also regulated in neurodegenerative diseases: UCHL-1, transhtyretin, Apolipoprotein A1, DRP-2 and DRP-3." (PMID 21470419, 2011). "The protection of ApoA1 from this neurodegenerative disease could not be a mere reflection of its beneficial systemic effect." (PMID 34071695, 2021).
bacterial infection (7 papers, 2019 to 2025). "Enrichment analysis showed that SPINK1+ HCC and APOA1+SPINK1+PLA2G2A+ HCC cells were significantly involved in bacterial infection-related pathways." (PMID 37333982, 2023).
infectious disease (6 papers, 2016 to 2025). A disorder directly resulting from the presence and activity of a microbial, viral, or parasitic agent in humans. "Moreover, acute-phase protein serum levels including α2-macroglobulin, haptoglobin, apolipoprotein A1 have been increased during the inflammatory reaction, and their components contribute to innate immune reaction against infectious diseases." (PMID 34422155, 2021).
brain diseases (4 papers, 2015 to 2025). "Based on the multifunction of these proteins in several brain diseases, we first propose that Gc-globulin, ApoA1, PI3K/AKT pathway, and acute phase response proteins (hemopexin and cluster of alpha-2-macroglobulin) could be potential candidates for the diagnosis and treatment of SAE." (PMID 36600206, 2023).
gynecological tumors (3 papers, 2020 to 2025). "Although there has been minimal research conducted on the immunological function of APOA1 during gestation, discoveries gained from gynecological tumor studies may provide some insights into this area." (PMID 40778280, 2025).
respiratory diseases (3 papers, 2018 to 2023). "Important roles for apolipoprotein A1 have been reported in the modulating pathogenesis of many respiratory diseases, such as attenuating inflammation, oxygen stress or bronchoalveolar lavage." (PMID 32987960, 2020).
retinopathy (3 papers, 2017 to 2024). "Hence, the increase of ApoA1 and ApoE in the EXE group may have a positive effect against the development of retinopathy, which is the leading cause of morbidity and disability in older diabetic patients." (PMID 28713486, 2017).
hematologic malignancies (2 papers, 2023 to 2025). "One large cohort study comprising 116,728 individuals found an inverse association between the incidence of certain hematologic malignancies, including MM, and the levels of high-density lipoprotein cholesterol (HDL-C) and its crucial component, apolipoprotein A1." (PMID 37836494, 2023).